BRAF (B-Raf proto-oncogene, serine/threonine kinase)
Diseases named in the same sentence as BRAF in open-access papers (continued):
Sharing a sentence is not in itself a finding about the gene and the disease.
melanoma (continued). "This review highlights the mechanisms of BRAF inhibitor resistance in melanoma and discusses the current state of its therapeutic approaches that can be further explored in clinical practice." (PMID 36181568, 2022). "Trametinib is an MEK inhibitor that inhibits the MEK and ERK signaling pathways and has been approved for use in the treatment of BRAF-mutant cancers, such as melanoma and anaplastic thyroid cancer, in combination with the BRAF inhibitor dabrafenib." (PMID 36336681, 2022). "Other evidence recently confirmed the advantage of the use of CHK1 inhibitors in melanoma cells both sensitive and resistant to BRAF inhibitors." (PMID 35563772, 2022). "In this regard, ongoing studies in our laboratory aim to confirm that BRAF is degraded by the 26S proteasome in melanoma cells." (PMID 36009541, 2022). "In spite of these data, for BRAF mutant melanoma patients with large bulky tumors, BRAF/MEK inhibitors are frequently used to reduce tumor size before initiating immune checkpoint inhibitor." (PMID 35806358, 2022). "For example, while inhibition of BRAF or MEK in A375 melanoma cell line resulted in activation of the YAP/TAZ pathway, the effect of BRAF/MEK inhibition in the SK-MEL-5 cell line resulted in inhibition of the YAP/TAZ pathway." (PMID 35585055, 2022). "We next assessed changes in expression of the RNA binding, transport and translation gene set using a published transcriptomic analysis of melanoma patients progressing after treatment with BRAF ± MEK inhibitor treatment." (PMID 35232962, 2022). "In vivo melanoma models have shown tumor growth delay, reduced tumor size and prolonged overall survival with the combination of anti-PD-1/anti-PD-L1 and BRAF and MEK inhibitors." (PMID 35495634, 2022). "The observed RAS-binding domain deletion is one of 9 so far identified with BRAF deletions spanning the exons from 2 to 10, with the 2–8 deletion being dominant in melanoma." (PMID 35883549, 2022). "To explore the possible mechanism of lj‐2‐66’s anti‐BRAF‐mutant melanoma activity effect, we evaluated the cell cycle and apoptosis in melanoma cells treated with 50 and 100 nM lj‐2‐66 for 48 h by flow cytometry." (PMID 35332658, 2022). "To examine the effect of KDs on melanoma growth, we established BRAF mutant (A375 and WM47), BRAF/NRAS/NF1 wild-type (WM3311), and NRAS mutant (WM3000) xenografts in CD-1 nude mice." (PMID 35851093, 2022). "Our results demonstrate that front-line treatment with CPI is associated with favorable tumor control and overall survival in patients with BRAF-mutant melanoma." (PMID 35565212, 2022). "Pediatric tumors with BRAF mutation partially overlap the spectrum of adult tumors with the same mutation; the BRAF V600E mutation in particular can be found in Langerhans Cell Histiocytosis (LCH), papillary thyroid carcinoma and melanoma." (PMID 36077798, 2022). "In 2011, the FDA approved the first targeted drug for the treatment of advanced melanoma, the BRAF protein inhibitor vemurafenib." (PMID 35565444, 2022). "We selected some BRAF- and NRAS-mutated cell lines such as SkMel28, A375 and Mel Juso to study the role of UBIAD1 in the antioxidant defense of melanoma." (PMID 35255427, 2022). "Molecularly targeted therapies to target BRAF mutant melanomas are thus gaining clinical interest and significance." (PMID 35954441, 2022). "Melanoma cells harbouring BRAFV600E/K are addicted to BRAF activity, explaining the striking clinical response to BRAFi." (PMID 35903549, 2022). "Simvastatin improved the inefficiency of vemurafenib (BRAF inhibitor) or selumetinib (MEK inhibitor) as an anti-cancer agent in MAPK mutant melanoma by inhibiting isoprenoid synthesis." (PMID 34065757, 2021). "Melanoma cell apoptosis induced by ECCA was further verified using another melanoma cell line, Mel-Juso, which harbors mutated NRAS and wild-type BRAF genes." (PMID 34103468, 2021).
melanoma (continued). "The combination of dabrafenib/trametinib received FDA approval in 2018 as an adjuvant treatment for BRAF V600E-mutated, stage III melanoma after surgical resection." (PMID 34771633, 2021). "Re-establishment of miR-181a/b expression reverses the resistance of melanoma cells to the BRAF inhibitor dabrafenib." (PMID 33670365, 2021). "The loss of the CDKN2A locus also cooperates with Cyclin D1 in promoting resistance to BRAF inhibitors in melanoma." (PMID 34066022, 2021). "BRAF V600E is a gene marker for vemurafenib therapy in melanoma, which can also be used in ovarian cancer." (PMID 34771633, 2021). "The study also suggested that combined BRAF and MEK inhibition with PD-1 blockade immunotherapy in BRAF-mutant melanoma can increase the frequency of long-lasting antitumor responses." (PMID 35003090, 2021). "However, molecular analyses and functional studies showed that melanomas could become resistant to single-agent BRAFi treatment though the development of amplification of Braf and through mutations that produced splice variants of the BRAF protein." (PMID 34859235, 2021). "Patients with BRAF-mutant (BRAF-mt) melanoma benefit significantly from treatment with BRAF inhibitors and onset of response is often rapid." (PMID 33915880, 2021). "Well-studied examples include BRAF V600E in melanoma, IDH1 R132H in low-grade glioma and KRAS G12D in pancreatic and colorectal cancer." (PMID 33556087, 2021). "The KEYNOTE-006 study, evaluating the efficacy of pembrolizumab in BRAF V600-mutant melanoma patients, reported a 5-year median OS of 32.7 months (95% CI 24.5–41.6)." (PMID 33801689, 2021). "In fact, BRAF-inhibitors-resistant melanoma cells increase uptake of glutamine and show overexpression of glutaminase (GLS)." (PMID 34073463, 2021). "With respect to melanoma, BRAF alteration is the main driver although there is a broad range of pathogenic mutations described." (PMID 33947144, 2021). "We found that eIF3a was downregulated in vemurafenib-resistant A375 cells, and its depletion significantly decreased the response of melanoma cells to BRAF inhibitors." (PMID 34512348, 2021). "Recent observations demonstrate that BRAF inhibitors induce reactive oxygen species in melanoma cells." (PMID 33451139, 2021). "It was found that accordance between tissue and plasma BRAF(V600E) ranged from 75% to 84%, making its quantification a reliable biomarker in melanoma." (PMID 34575876, 2021). "All CASCADE patients had BRAF mutant melanomas and received BRAF and/or MEK inhibitors during their disease course, with some also receiving immunotherapy." (PMID 33664264, 2021). "Since that initial discovery, targeted therapies have been developed for the treatment of melanoma, such as BRAF and MAP2K1/2 inhibitor drugs." (PMID 34831420, 2021). "BRAF-mutant melanomas are more likely than NRAS-mutant melanomas to arise in anatomical locations protected from chronic sun damage." (PMID 34210801, 2021). "Though there is disagreement on the specific correlations between melanoma metastasis and BRAF/NRAS mutation status, BRAF and NRAS mutations are known to be stage-independent risk factors for worse prognosis in the metastatic setting." (PMID 35008286, 2021). "BRAF inhibitor-resistant melanomas induced expansion of CCR2-expressing monocytic-MDSCs in the TME by producing CCL2, activating MDSCs through MAPK signaling." (PMID 34095111, 2021). "Oncogenic BRAF elicits metabolic reprogramming in melanoma cells consistent with the classical Warburg effect, whereby increased aerobic glycolysis and decreased reliance on oxidative metabolism are observed." (PMID 33572972, 2021). "For example, CTCs were detected in smaller numbers in patients with metastatic BRAFv600E melanoma and declined after BRAF‐targeted therapy." (PMID 33448107, 2021). "Based on these models, we suggested miR-205,-203,-9, and -15b as common regulators of EMT, self-renewal, and BRAF pathways in melanoma." (PMID 34308569, 2021).
melanoma (continued). "Of note, the authors also identified plexinB1 as a target gene inhibited by BRAF signaling both in melanocytes and in melanoma cells, suggesting the induction of a permissive environment by BRAF/MEK axis through modulation of plexinB1." (PMID 33858502, 2021). "Cell apoptosis is a key biological process in the inhibition of proliferation of BRAF V600 mutant melanoma induced by vemurafenib." (PMID 34222023, 2021). "Synergistic effects and delayed acquisition of resistance have also been shown with the combination of vemurafenib (BRAFi) and SCH722984 (ERKi) in BRAF mutant melanoma cells." (PMID 33672955, 2021). "At present, the high and rapid response rates as well as good safety profile of BRAF-targeted agents offer an unprecedented opportunity for a neoadjuvant approach in melanoma treatment." (PMID 33777924, 2021). "In cases where BRAF is inhibited, CRAF can activate downstream MAP2K1 with RAS mutation in melanoma." (PMID 34831420, 2021). "Patients with BRAF-positive advanced melanoma are offered additional first-line treatment options, namely combined BRAFi plus MEKi regimens." (PMID 34914610, 2021). "Downregulation of IFNAR is found during tumor development in melanoma patients and expression of a non-degradable IFNAR1 mutant in mice was shown to delay the formation and progression of melanoma and increase responsiveness to BRAF or PD-1 inhibitors in vivo." (PMID 33801234, 2021). "A phase 3, randomized open-labeled study named BRIM-3 assessed the effects of Vemurafenib on patients with BRAF-V600E- and BRAF-V600K-positive melanoma in comparison to the cytostatic Dacarbazine." (PMID 33917267, 2021). "While BRAF inhibitors have shown some improvement in survival for melanoma therapy, advanced melanoma patients are still faced with low five‐year survival rates." (PMID 33377602, 2021). "They studied 176 lesions, including 18 lung lesions from 70 patients with melanoma (35 BRAF-mt and 35 BRAF-wt)." (PMID 33915880, 2021). "Given the molecular rationale that BRAF mutation robustly triggers the hyper-activation of downstream MEK-ERK pathway, MEK-targeted agent trametinib has then been developed for melanoma targeted therapy." (PMID 34924562, 2021). "We demonstrated that the plasma membrane Ca2+ ATPase PMCA4b inhibits migration and metastatic activity of BRAF mutant melanoma cells." (PMID 33802790, 2021). "Recently, the combination of atezolizumab, vemurafenib, and cobimetinib have been approved by the FDA as first-line treatment for unresectable advanced BRAF V600 mutant melanoma and showed a significant increase in progression-free survival in patients." (PMID 33807778, 2021). "A study compared a pair of BRAF mutant human melanoma cells: LM36, which is sensitive to vemurafenib, and LM36R, which is vemurafenib resistant." (PMID 34831420, 2021). "RAC1 mutant human melanoma cells are resistant to clinical inhibitors of BRAF but are uniquely sensitive to PAK inhibitors." (PMID 34827551, 2021). "As EGFR pathway activation is so strongly connected to BRAF/MEK inhibitor resistance in melanoma, it is likely that stress-induced NRF2 activation during therapy significantly contributes to this effect." (PMID 33916908, 2021). "Previously, we identified the PMCA4b Ca2+ pump as a putative metastatic suppressor in BRAF mutant melanoma cells." (PMID 33802790, 2021). "For instance, BRAF inhibitor-resistant melanoma cells are observed to have elevated reactive oxygen species (ROS) and correspondingly display higher levels of the reactive oxygen detoxification enzyme SOD2." (PMID 34831420, 2021). "The combination of the BRAF inhibitors vemurafenib and GSK2816126 revealed a more significant anticancer effect than vemurafenib monotherapy in melanoma models with both a BRAF V600E mutation and an EZH2 abnormality." (PMID 34001246, 2021). "Tumors are notorious for evolving mechanisms to avoid immune surveillance, and oncogenic BRAF in melanoma cells can induce changes that facilitate tumor immune escape." (PMID 34025662, 2021).
melanoma (continued). "Together with our previous finding that SBI-756 can circumvent resistance to BRAF inhibitors in melanoma, these results support further combination studies of SBI-756 with other targeted agents." (PMID 33318657, 2021). "The first, panicein A hydroquinone (PAH), a compound purified from a marine sponge, increases the cytotoxicity of dxr and of the BRAF inhibitor vemurafenib against melanoma cells in vitro and in vivo." (PMID 33810240, 2021). "Combination treatment using BRAF/MEK inhibitors is a promising therapy for patients with advanced BRAFV600E/K mutant melanoma." (PMID 34885166, 2021). "The identification of common mutations in BRAF, NRAS and NF1 indicated that the RAF-MEK-ERK pathway is a crucial driver of melanoma." (PMID 33549048, 2021). "JQ1 not only potently impairs tumor cell proliferation, cell transformation and in vivo tumor growth in YAP/TAZ-addicted breast, liver and pancreatic cancer models; but also sensitizes BRAF-mutant melanoma cells to vemurafenib treatment." (PMID 33467099, 2021). "Multiple retrospective studies have demonstrated high efficacy rates of BRAF inhibitors combined with SRS for patients with melanoma BM, overcoming the preconceived notions of radioresistance." (PMID 34359583, 2021). "Our study provides a molecular mechanism by which BRAF-mutant melanoma cells gain resistance to BRAFi and MEKi combination therapy, and implicates mTOR inhibition for further treatment of CR patients." (PMID 34304249, 2021). "BRAF and NRAS mutations are common in benign nevi, suggesting that additional mutations are required to drive melanoma progression in those tumors." (PMID 35008286, 2021). "Melanoma cells produce isomers that lack exons 4–8 of BRAF (V600E), which allows them to avoid the effects of drugs." (PMID 34249669, 2021). "BRAF fusions are estimated to occur in 3–6% of all melanoma patients, with a higher frequency in female gender, younger age and certain histopathologic subtypes such as spitzoid melanomas." (PMID 33801689, 2021). "BRAF mutant melanoma accounts for nearly 50% of metastatic melanoma cases, among which V600E mutant represents 84.6% of the BRAF mutations." (PMID 33841154, 2021). "The cooperation of oncogenic BRAF kinase mutation with inactivated tumor suppressor PTEN activates both the MAPK and PI3K pathways to promote the progression of melanoma and metastasis." (PMID 34282258, 2021). "We found that the nevogenic melanomas were associated with mutations in BRAF, while the CSD melanomas were associated with mutations in NF1, ROS1, GNA11, and RAC1." (PMID 34680367, 2021). "In BRAF inhibitor-resistant melanoma, high dependence on mitochondria for survival, with increased OxPhos and mitochondrial biogenesis were observed." (PMID 33804114, 2021). "A second group of “driver” mutations involves the small GTPase Neuroblastoma rat sarcoma viral oncogene homolog (NRAS) proto-oncogene, representing 15–20% of all the BRAF-WT melanoma patients." (PMID 34207514, 2021). "In fact, various BRAF and MEK1/2 inhibitors are under clinical investigation and a handful have been improved for use in BRAF-mutant melanoma." (PMID 33801965, 2021). "Tas and Ertuk analyzed the prognostic significance of BRAF V600E mutation in 151 stage III patients; a BRAF mutation was present in 51% of melanomas and was associated with better OS and longer disease-free survival." (PMID 33925387, 2021). "Patients with melanoma lung metastases, known BRAF status, and a pretreatment computed tomography scan were included." (PMID 33915880, 2021). "pri-miR-29b1~a expression varied considerably between cell lines with a trend toward reduced expression in melanoma cells compared to BRAF-mutant melanocytes." (PMID 33808771, 2021).
melanoma (continued). "The strong efficacy of CRO15 to reduce the growth of melanoma xenograft sensitive or resistant to BRAF inhibitors opens interesting perspective." (PMID 33431809, 2021). "Oncogenic BRAF, NRAS, NF1 mutations can activate the tyrosine kinase receptor EGFR resulting in enhanced ERK1/2 phosphorylation in melanoma." (PMID 34360915, 2021). "A panel of melanoma cell lines, harboring wild type or mutant BRAF and NRAS, showed sensitivity to the six EOs, even if at a different extend, thus indicating that the effect of EOs was not related to BRAF or NRAS status." (PMID 34059622, 2021). "A number of MEK inhibitors, including selumetinib, trametinib, cobimetinib, and binimetinib, have been studied as monotherapy or in combination with BRAF inhibitors for the treatment of melanoma." (PMID 33807778, 2021). "Although many new treatments for melanoma have been approved in recent years, including immune checkpoint inhibitors and BRAF/MEK inhibitors, limited data are available for survival for patients with brain metastases treated with these novel therapies." (PMID 33804910, 2021). "The uptake of BRAF siRNA in melanoma tissue has been observed, resulting in regressing the tumor growth in mouse melanoma models." (PMID 33777924, 2021). "In the phase 3, randomized trial in patients with BRAF-mutant melanoma, encorafenib plus binimetinib showed a favorable efficacy and safety profile compared with vemurafenib monotherapy." (PMID 34064013, 2021). "Combinations of BRAF and MEK inhibitors have emerged as new treatment options for patients with BRAF-mutated melanoma with a good response rate." (PMID 34680222, 2021). "Having elaborated that miR-129-5p functions as tumor suppressor and mediates BRAF inhibitor treatment response, we investigated potential target genes, known to be involved in melanoma progression and drug resistance." (PMID 34063443, 2021). "In general, mutant NF1 melanoma contain WT BRAF and WT NRAS, and rather carry comutations in the so-called RASopathy genes (PTPN11 or RASA2)." (PMID 34362135, 2021). "Owing to tumor heterogeneity, in melanoma, a subset of mutant BRAF cells was found to be intrinsically resistant to MAPK inhibitors." (PMID 33804114, 2021). "First, we analyzed the effects of depletion of the candidate genes in the BRAF‐mutant melanoma cell line WM983B that was included in the CRISPR‐Cas9 screens performed by the Broad institute." (PMID 32767816, 2021). "There is evidence of senescence or a senescence-like phenotype throughout the progression of BRAF mutant melanoma." (PMID 34066966, 2021). "Mutant Ras and BRAF genes have been found in some cancers, such as melanomas, and play a key role in the growth and spread of cancer cells." (PMID 34205739, 2021). "There is currently no clinical trial data to determine what is the optimal sequence for treating advanced BRAF mutant melanoma patients." (PMID 34677256, 2021). "Patients with BRAF wild-type melanomas had improved survival with ipilimumab and nivolumab versus those treated with a single-agent PD-1 inhibitor (median OS not reached and 21.2 months)." (PMID 34677256, 2021). "In recent years, melanoma treatment has included conventional chemotherapy and radiation therapy and therapies targeting B-raf proto-oncogene, serine/threonine kinase (BRAF), and MAP kinase-ERK kinase." (PMID 34220795, 2021). "With the identification of BRAF and its significant role in melanoma, therapies have been developed to target its specific inhibition." (PMID 34441278, 2021). "We further show that the recovery of mTORC1 activity represents a therapeutic vulnerability for CR BRAF-mutant melanoma." (PMID 34304249, 2021).